SLC71A2 (solute carrier family 71 member 2)
Description:
Probable membrane-bound transporter. May play a role in neuronal nutrient sensing and energy homeostasis.
Synonyms: HIATL1; MFSD14B; FLJ14753
Tractability: Antibody: UniProt predicts a signal peptide or a membrane-spanning region. PROTAC: ubiquitination databases record sites on it.
Gene: Protein-coding gene on chromosome 9 (94,374,403 to 94,461,042, forward strand). Ensembl gene ENSG00000148110.
Subcellular location: Endoplasmic reticulum membrane
Subcellular location (Human Protein Atlas): Cytosol; Nucleoplasm
Gene Ontology:
Molecular function: protein binding; transmembrane transporter activity
Biological process: transmembrane transport
Cellular component: endoplasmic reticulum membrane; membrane
Genetic constraint (gnomAD): Loss-of-function variants: 19 observed, 33.13 expected, observed/expected ratio (o/e) 0.57, 90% interval 0.4 to 0.84. The upper end of that interval is the gene's LOEUF score, 0.84, which puts it in group 3 of 6, group 1 being the genes least tolerant of losing a copy. Missense variants: 366 observed, 450.33 expected, observed/expected ratio (o/e) 0.81, 90% interval 0.75 to 0.89. Synonymous variants: 184 observed, 173.44 expected, observed/expected ratio (o/e) 1.06, 90% interval 0.94 to 1.2.
Homologues: Orthologues: chimpanzee MFSD14B (99% identical), macaque MFSD14B (99% identical), rabbit MFSD14B (95% identical), dog MFSD14B (93% identical), pig MFSD14B (92% identical), mouse Mfsd14b (90% identical), rat Mfsd14b (90% identical), guinea pig MFSD14B (77% identical), tropical clawed frog mfsd14bl (75% identical), zebrafish mfsd14bb (66% identical), Drosophila melanogaster CG11537 (54% identical), Caenorhabditis elegans T25D3.4 (52% identical), and 12 more. Paralogues in human: SLC71A1 (70% identical), SLC75A1 (19% identical), SLC67A2 (17% identical), MFSD1 (15% identical), MFSD8 (13% identical), SLC61A1 (12% identical).
Diseases named in the same sentence as SLC71A2 in open-access papers:
SLC71A2 is named in the same sentence as 6 diseases in open-access papers, as found by Europe PMC text mining. Sharing a sentence is not in itself a finding about the gene and the disease.
SLC71A2 shares sentences with these, for which no sentence is quoted: colorectal cancer (2 papers); cancer (1); colon tumor (1); Infertility (1); Obesity (1); tumor (1).